CCL2 (C-C motif chemokine ligand 2)
Diseases named in the same sentence as CCL2 in open-access papers (continued):
Sharing a sentence is not in itself a finding about the gene and the disease.
cancer (1,480 papers, 2007 to 2026). A tumor composed of atypical neoplastic, often pleomorphic cells that invade other tissues. "Once in circulation, M-MDSCs are recruited primarily through the CCL2/CCR2 axis, supported by CCL3 and CCL4, with cancer-associated fibroblasts amplifying this process by secreting CCL2." (PMID 41228234, 2025). "Elevated CCL2 levels have been linked to enhanced pain perception in cancer patients, indicating its relevance in pain mechanisms." (PMID 40579593, 2025). "Fusobacterium nucleatum (F. nucleatum) drives the transformation of adipocytes into a cancer-associated phenotype via autocrine CCL2 signaling." (PMID 41276817, 2025). "High CCL2 expression is also associated with aggressive malignancies, increased metastatic potential, and poor prognosis in various cancers." (PMID 40806751, 2025). "Research indicates that cancer‐associated fibroblasts (CAFs) secrete elevated levels of CCL2, CCL5, CCL7, and CXCL16, which facilitate the migration and invasion of HCC cells." (PMID 40062588, 2025). "In vitro, F. nucleatum induced the formation of cancer-associated adipocytes via autocrine C-C motif chemokine ligand 2 (CCL2), which stimulated lipolysis and enhanced free fatty acid release." (PMID 41276817, 2025). "A large number of pan-cancer analyses have shown that high levels of CCL2 are associated with more aggressive malignancies, higher risk of metastasis, and poor cancer prognosis." (PMID 41341593, 2025). "The levels of CCL2 detected in the culture supernatants of cancer-associated adipocytes cocultured with MCF-7 or MDA-MB-231 cells were higher than those in the normal breast adipocytes cocultured with BC cells." (PMID 41341593, 2025). "Meanwhile, −2518A/G (rs1024611) is the most widely studied CCL2 regulatory SNP and has the most well-defined function in tumors; its G allele rs1024611G is associated with high CCL2 expression and poor clinical prognosis in a variety of cancers." (PMID 41341593, 2025). "Cancer-associated fibroblasts (CAMs) promote the cancer stem cell (CSC) phenotype in cancer cells by secreting CCL2." (PMID 39318358, 2024). "The CCL2/CCR2 axis has been linked to poor prognosis in a wide range of cancers, including brain, gastric, pancreatic, breast, ovarian, prostate, esophageal, tongue, liver, colorectal, and gallbladder cancers." (PMID 39409924, 2024). "The overexpression of CCL2 in breast tumors has been linked to increased macrophage infiltration, enhanced cancer metastasis, and poor prognosis." (PMID 39409110, 2024). "Compared with normal fibroblasts, primary cancer-associated fibroblasts (CAFs) or fibroblasts activated by cocultured BC cells produced higher levels of CCL2, which stimulated the stem cell-specific sphere-forming phenotype in BC cells and CSC self-renewal." (PMID 37208442, 2023). "Of interest is a study showing sustained up-regulation of the chemokine CCL2 increased cancer susceptibility in a transgenic mouse model." (PMID 36656812, 2023). "In turn, cancer cells exposed to cancer-associated mesothelial cell-derived CCL-2 show increased migration and transmesothelial migration under 2-D culture conditions." (PMID 37545408, 2023). "A global gene expression analysis of CCL2 overexpressing mice revealed that CCL2 upregulates cancer-associated gene pathways and downregulates fatty acid metabolism gene pathways." (PMID 37108548, 2023). "For example, the CCL2/CCR2 axis has a vital role in the metastatic facilitating of TAMs, and an increased level of CCL2 is associated with many cancer types." (PMID 38017494, 2023). "Upregulation of CCL2, as shown in our data, has been associated with cancer advancement, metastasis, and relapse." (PMID 36831273, 2023). "CC chemokine 2 (CCL2) is a multifunctional factor associated with the progression of numerous cancers." (PMID 37445830, 2023). "VEGF-A, TNF-α, CCL2, and IL-6 were positively associated with muscle-associated enzymes among the Cancer TIF1-γ-DM patients." (PMID 36357631, 2023).
cancer (continued). "Plasma levels of CCL2 > 462.3 pg/mL were considered suitable to reflect cancer risk in anti-TIF1-γ antibody-positive DM patients." (PMID 36357631, 2023). "CCL2/MCP (Monocyte chemoattractant protein)-1 drives migration and invasion, and is implicated in cancer cell homing at the metastatic site." (PMID 36941406, 2023). "Suppression of CCL2 in EC associated with LKB1 mutations resulted in marked attenuation in cancer development." (PMID 35408440, 2022). "Among the chemokines reported in oncovirus-associated cancers, CCL2 and CXCL12 are known to directly support cancer cell stemness, proliferation, and survival." (PMID 35159113, 2022). "Although CCL2 was initially identified as a mediator of inflammation, increasing evidence has linked CCL2 with human diseases, particularly cancer." (PMID 34464477, 2021). "Cancer-associated mesenchymal stem cells (CA-MSCs) interact with neutrophils and enhance their CCL2 and TNFα production." (PMID 34386431, 2021). "The CCR5/CCL5 axis, apart from having a similar immunomodulatory role to CCR2/CCL2, has also been implicated in cancer progression and metastasis as well as a marker of poor prognosis in several cancers." (PMID 33546207, 2021). "And the CCL2/CCR2 axis has generated increasing interest in recent years due to its association with the progression of cancer." (PMID 34187403, 2021). "Loss of PTEN in cancer cells leads to the upregulated secretion of the chemokine CCL2, which recruits ionized calcium binding adaptor molecule 1 (IBA1)-expressing myeloid cells." (PMID 36046433, 2021). "Previous studies showed that the genes encoding CCL2 are downstream targets of the NF-κB transcription factor, which are crucial for cancer progression and metastasis." (PMID 33838681, 2021). "Increased COX-2 expression is linked to cancer progression and metastases and often coincides with an overexpression of CCL2." (PMID 34064859, 2021). "For example, IL-8 secreted by cancer-associated fibroblasts (CAFs), IL-17 secreted by Th17 cells and CCL2 secreted by mesenchymal stem cells (MSCs)." (PMID 34683963, 2021). "Antibody‐associated antigen neutralization of tumorigenic CCL2 suspends cancer development, giving a golden chance for the potent therapeutics of CCL2 blockades and neutralization antibodies in PDAC treatment and prevention." (PMID 34525267, 2021). "Although CCR2 antagonism in cancer is predominantly discussed in the context of solid tumors, the CCL2/CCR2 axis is also implicated in blood cancers." (PMID 34804061, 2021). "Because CCL2 and IL-8 chemokines have known roles in angiogenesis and cancer-associated inflammation, HA-CD44 signaling has important implications within human cases of TNBC." (PMID 32455980, 2020). "As CCL2 is secreted by bone marrow endothelial cells, it causes the diapedesis of cancer cells into the bone tissue." (PMID 33182504, 2020). "High levels of CCL2 have been associated with cancer progression in several types of cancer, including breast, prostate, colorectal, kidney, and thyroid cancers." (PMID 32429318, 2020). "CCL2 is highly expressed in various cancer types and has been shown to be associated with poor prognosis." (PMID 33247183, 2020). "In a study examining CCL2 expression in 87 hepatectomy specimens of colorectal cancer liver metastases, CCL2 levels were associated with cancer progression and were prognostic markers of survival after hepatectomy for colorectal liver metastases." (PMID 33297571, 2020). "The CCL2/CCR2 recruitment mechanism is implicated in a number of cancers and a CCR2 inhibitor to be administered alongside chemotherapy is currently in phase 1b trials." (PMID 32038499, 2020). "In contrast, the expressions of the cancer-associated proteins FAPα and CCL-2 in the CACs were more pronounced than the normal colon tissue." (PMID 31920487, 2019).
cancer (continued). "Here, the authors show that cancer cells with KRAS mutations promote MPE by recruiting myeloid cells via CCL2 signalling and that pharmaceutical targeting of KRAS results in reduced MPE incidence and volume in mouse models." (PMID 28508873, 2017). "This study investigated the significance of CCL2 in regulating macrophage recruitment, healthy mammary gland development, and the risk of cancer." (PMID 28077158, 2017). "Constitutive expression of CCL2 by the mouse mammary epithelium induces a state of low level chronic inflammation that perturbs collagen remodelling and elevates cancer risk." (PMID 28077158, 2017). "CXCL1, MMP9, IL1B, WNT7A, and CCL2 were associated with cancer malignant characteristics which were remarkably decreased in Top 10 list." (PMID 28881805, 2017). "This in turn leads to activation of transcription of chemokines such as CCL2 which is associated with poor prognosis in breast and other cancers." (PMID 27058619, 2017). "Constitutive expression of CCL2 by the mouse mammary epithelium induces a state of low level chronic inflammation that increases stromal density and elevates cancer risk." (PMID 28077158, 2017). "As a cautionary note, a recent study in breast carcinoma demonstrated that interruption of CCL2 inhibition was associated with increased cancer cell mobility and blood vessel formation, leading to accelerated metastasis and cancer death." (PMID 28360914, 2017). "Recent researches have clarified that overexpression of CCL2 is associated with unfavorable prognosis in various cancer types." (PMID 27409666, 2016). "CCL2 is also associated with the development and progression of several cancer types, including breast, ovarian and prostate." (PMID 27820834, 2016). "CCL2 has also been reported to be an important mediator of the enhancement of OSCC growth by cancer-associated fibroblasts." (PMID 25635769, 2015). "Recent report pointed out that CCL2 was one of the most highly and transiently expressed chemokines during inflammation and implicated in the pathogenesis of cancer metastasis." (PMID 25993304, 2015). "CCL2 additionally promotes epithelial to mesenchymal transition and is linked to cancer cell migration and cancer progression." (PMID 24887580, 2014). "Recently, cancer associated fibroblasts (CAFs) were found to secret chemokine (C-C motif) ligand 2 (CCL2) and stimulate the stem cell-specific, sphere-forming phenotype and BCSC self-renewal through induction of NOTCH1 expression." (PMID 24977105, 2012). "TAMs are actively recruited and conditioned by the tumor: cancer cells and stromal cells, like cancer-associated fibroblasts, secrete CCL2 and colony stimulating factors that recruit monocytes and induce their differentiation into MDSCs and M2 TAMs via STAT3-activating cytokines (IL-6, etc.)." (PMID 40227782, 2025). "Interestingly, lamin-deficient cancer cells were found to present higher expression levels of many inflammatory chemokines such as CCL2, CCL9, CCL22, CXCL9, and CXCL10." (PMID 40708945, 2025). "Furthermore, astrocytes transfer PTEN-targeting miR-19a via exosomes, promoting PTEN loss in cancer cells, in turn enhancing CCL2 secretion and promoting chemotaxis of ionized calcium-binding adapter molecule 1 (IBA1)+ myeloid cells." (PMID 41429896, 2025). "The observed anticancer polarization of these cancer-associated fibroblasts in response to treatment may be related to a reduction in CCL2, TNC, MMP9 and MMP-2." (PMID 41009006, 2025). "These nanoparticles suppressed cancer-associated fibroblasts (CAFs) and inhibited CCL2 secretion by cancer-associated adipocytes (CAAs), leading to enhanced cytotoxic T-cell infiltration and decreased levels of immunosuppressive cells, ultimately resulting in potent antitumor effects." (PMID 40572668, 2025).
cancer (continued). "For example, carlumab, an antibody against CCL2, has been tested in clinical trials and using carlumab in association with conventional chemotherapy demonstrated preliminary antitumor activity in patients with advanced cancer." (PMID 39195299, 2024). "CCL2 is also over-expressed in a wide range of cancers and is associated with poor prognosis." (PMID 39459945, 2024). "Furthermore, cytokines Ccl2, Ccl4, Ccl7, Ccl22, and Il21r, which associated with an M2-like, pro-cancer macrophage phenotype, were found to be consistently downregulated at both days 5 and 10 post-challenge." (PMID 37066426, 2024). "Moreover, 6‐shogaol prevents cancer progression by inhibiting the secretion of CC‐chemokine ligand 2 (CCL2) in tumor‐associated dendritic cells (TADCs)." (PMID 39055196, 2024). "CCL2 derives from hypoxic primary cancer and is associated to immunosuppression which characterizes the lung premetastatic niche by promoting the infiltration of dysfunctional myeloid and NK cells with decreased capacity to eliminate incoming invasive tumor cells." (PMID 39469649, 2024). "Indeed, cancer cells produce chemokine CCL2 a potent chemoattractant for monocytes, macrophages, memory T lymphocytes, and natural killer (NK) cells which is known to be implicated in cancer progression." (PMID 39469649, 2024). "Importantly, upregulation of CCR2 and its ligand CCL2 has also been found in PCa and associated with cancer advancement, metastasis, and relapse, and upregulation of CCL18 has been shown to correlate with malignant progression of PCa." (PMID 36321189, 2023). "The importance of cancer cell-derived CCL2 may be further clarified by using CCL2-deficient BC cells." (PMID 37208442, 2023). "The selected haplotypes for CCL5 and CCL2 SNPs also correlated with an increased risk of cancer." (PMID 38001676, 2023). "TIF1-γ mutation or overexpression in cancer cells was hypothesized activate CCL2 and TNF-α expression." (PMID 36357631, 2023). "Because LGR5 may have different properties than other cancer stem cell markers, there is an association between low LGR5 expression in fat invasion and cancer-associated adipocytes, especially CCL2, which may result in EMT." (PMID 35123536, 2022). "CCL2 is reported to be associated with various cancers and has recently attracted much attention." (PMID 36289628, 2022). "C-JUN, a proto-oncogene (its protein is JUN), is a cellular homologue of viral oncoprotein v-JUN, which is the major carcinogenic transcription factor found, and CCL2 can not only maintain the drug resistance of drug-resistant cancer cells but also cause drug resistance of sensitive cancer cells." (PMID 35321506, 2022). "However, a recent study discovered that interruption of C–C motif chemokine ligand 2 (CCL2) inhibition was associated with increased cancer cell mobility and neovascularization, leading to accelerated metastasis and cancer death." (PMID 34267763, 2021). "MCP1 (also known as CCL2) is a monocyte-attracting cytokine in cancer associated with TAMs." (PMID 35008176, 2021). "CCL2 derived from cancer‐associated mesothelial cells could elevate ovarian cancer malignant potential, which was dependent on p38‐MAPK signalling." (PMID 34464477, 2021). "Finally, CPEB3 prevented secretion of CCL2 molecules in cancer cells and caused a reversion of the polarity of M2 macrophages." (PMID 34944712, 2021). "In addition, cancer-associated adipocytes secrete chemokines such as Chemokine (C–C motif) ligand 2 (CCL2), which activates NOTCH1 signaling pathway and induces the stemness of the cancer cells." (PMID 32796516, 2020). "In addition to the macrophage infiltration, the CCL2-mediated signaling axis has been implicated to the metastatic process in various cancers." (PMID 31811337, 2020). "Angiogenesis may also be indirectly caused by the CCL2-mediated increase in VEGF expression in a cancer cell." (PMID 33182504, 2020).
cancer (continued). "Consequently, the loss of CCL2 expression in cancer cells significantly decreased the total myeloid cells, monocytes and macrophages infiltration but not neutrophils." (PMID 31780645, 2019). "Other types of cancer also cause stage-dependent increases in serum CCL2." (PMID 31823764, 2019). "It has also been elucidated that in bone marrow-derived stromal cells (BMSCs), loss of FBXW7 induced cancer metastasis via upregulation of the chemokine CCL2, which increased the monocytic myeloid-derived suppressor cells (Mo-MDSCs) as well as tumor-associated macrophages (TAMs)." (PMID 30791487, 2019). "Furthermore, in mouse CRC model, cancer-associated fibroblasts with high FAPα expression induce resistance to immune checkpoint blockade by up-regulating C–C motif chemokine ligand 2 (CCL-2) secretion, recruiting myeloid cells, and decreasing T-cell activity." (PMID 31920487, 2019). "Among the many chemokines associated with cancer progression, CCL2/CCR2 signaling may be considered a major player in promoting tumorigenesis and metastasis." (PMID 30871117, 2019). "Nevertheless, CCL2‐activated TAMs are associated with a poor prognosis in cancer." (PMID 29930175, 2018). "EVs generated by cancer cells promoted the polarization of macrophages to an inflammatory phenotype, characterized by the upregulation of several M1-associated genes (IL-1β, IL-8, CCL2, CXCL2) and the downregulation of MRC1 expression, an M2-related marker." (PMID 28600520, 2017). "Less understood is the role of CCL2 in healthy breast development and how this may relate to the risk of cancer initiation." (PMID 28077158, 2017). "Combined, these findings suggest that high mammographic density and the associated increased cancer risk may be the result of CCL2-driven inflammation." (PMID 28077158, 2017). "In addition, attenuating or blocking the release of CCL2 resulted in preventing cancer-associated inflammation." (PMID 27529277, 2016). "Cancer-associated fibroblasts secrete high levels of pro-inflammatory cytokines, including IL-1β, IL-8, IL-10, tumor necrosis factor-alpha (TNFα), monocyte chemoattractant protein-1 (MCP-1/CCL2), SDF-1/CXCL12 and interferon-beta (IFN-β), which have a range of effects on the immune system." (PMID 26828520, 2016). "Notably, several of the cytokines whose expression was upregulated in parenchymal cancer cells (e.g. CCL2, CCL7, CXCL1, CXCL2, CXCL5, CCL20) have been implicated in the attraction of immune cells." (PMID 27203741, 2016). "We also demonstrated the significance of CCL2 in EMT-associated cancer metastasis." (PMID 25883937, 2015). "As angiogenesis has a critical role in the metastatic process, which is the primary cause of mortality in cancer patients, the down-regulation of chemokine (C-C motif) ligand 2 (CCL2) and vascular endothelial growth factor A (VEGFA), subsequent to AhR knockdown was deemed of high significance." (PMID 24932473, 2014). "Furthermore, three SNPs in CCL2 were found to be associated with high Gleason score (>7), one of which was associated with pathological staging, supporting a role of CCL2 in cancer development and progression." (PMID 23698775, 2013). "In addition, we observed a significant interaction between AA and EA women for the association of CCL2-rs4586 with risk of ER positive cancers in the larger data set (P for interaction=0.04)." (PMID 23991131, 2013). "Both CCL2 and IL-6 have been implicated in the process of cancer metastasis." (PMID 21826248, 2011). "However, since IL-6 and CCL2 have different receptors, the signaling pathways associated with the differences in ligand expression on the active receptors on the cancer cell surface may have been different." (PMID 40430040, 2025). "Thus, the association between serum CCL2 levels and different cancers appears to be variable." (PMID 31823764, 2019).